CD44 (CD44 molecule (IN blood group))
Diseases named in the same sentence as CD44 in open-access papers (continued):
Sharing a sentence is not in itself a finding about the gene and the disease.
prostate carcinoma (continued). "It has also been shown that CD44+CD133+ integrin α2β1high cells represent the tumorigenic cells from prostate cancer patients." (PMID 18268494, 2008). "The recent identification of the IGS as a prognostic indicator in prostate cancer and the correlation with its presence in a subset of the LNCaP cell line, suggest that CD44+CD24− LNCaP cells can serve as a model system." (PMID 18268494, 2008). "Using flow cytometry, we isolated a population of CD44+CD24− prostate cells that display stem cell characteristics as well as gene expression patterns that predict overall survival in prostate cancer patients." (PMID 18268494, 2008). "Previously, CD44+ prostate cancer cells were shown to have the stem-like properties of increased tumorigenic, clonogenic, and metastatic potential." (PMID 18268494, 2008). "Since our CD44+CD24− cells were isolated from a prostate cancer cell line, we searched for the presence of the IGS in our LNCaP tumour-initiating cells." (PMID 18268494, 2008). "We identified a CD44+CD24− subpopulation with varying abundance in different prostate cancer cell lines." (PMID 18268494, 2008). "Observation in different PC3 cell lines indicate an underlying correlation between the surface levels of CD44 and secretion of active form of MMP- 9 in prostate cancer cells." (PMID 17343740, 2007). "Adhesion of breast and prostate cancer cells to bone marrow endothelial cell line (hBMECs) is directly related to the surface expression of the hyaluronan receptor CD44." (PMID 17343740, 2007). "The standard form of CD44 is also a candidate metastasis suppressor gene located on chromosome 11p13, with potential involvement in prostate cancer progression through decreased expression." (PMID 11953827, 2002). "Notably, the anti-CD44 monoclonal antibody bivatuzumab, which has been investigated in head and neck squamous cell carcinoma and prostate cancer, shows promising potential for broader oncological applications." (PMID 40332380, 2025). "We found that CD133 and CD44 can serve as stemness markers in prostate cancer." (PMID 40923331, 2025). "Silencing CD44 restored docetaxel sensitivity, indicating its possible use as both a predictive biomarker and a therapeutic target in treatment-resistant castration-resistant prostate cancer." (PMID 41440277, 2025). "In addition, the growth of prostate cancer tumorsphere cells was also inhibited by genistein (in vitro studies) through the down-regulation of CD44 markers and the inhibition of the Hedgehog signaling pathway." (PMID 39859345, 2025). "In the subsequent step, Western Blot analyses confirmed the expression of the target proteins CD44 and EpCAM in the prostate cancer cell line PC3-PSMA and the prostate cancer stem cell-like (PCSC-like) cell line PC3-MM2, whereas the control cell line CHO showed no expression of either antigen." (PMID 39846613, 2025). "Accumulating evidence suggests that CD44 is a stem cell marker in prostate cancer." (PMID 38783892, 2024). "In addition, in docetaxel‐resistant prostate cancer cells, CD44 was reported to promote cell migration and invasion via induction of Hippo–YAP pathways." (PMID 38783892, 2024). "However, there is evidence that calcitonin can increase CD44 variant RNA and protein levels via p38 pathway in CALCR-positive prostate cancer cell." (PMID 38985127, 2024). "CD44+ prostate cancer cells that resemble stem cells invade and disseminate in vitro and in vivo." (PMID 38496894, 2024). "Notably, studies have highlighted a positive correlation between heightened CD44 levels and adverse prognostic outcomes in various cancers, including breast cancer, colorectal cancer, pancreatic carcinoma, and prostate cancer." (PMID 38542115, 2024). "Furthermore, it is observed that prostate cancer stem cells which are resistant to docetaxel, are characterized by the presence of CD44+ and CD133+ and stemness-related genes." (PMID 39003454, 2024). "In prostate carcinoma, CD44 acts as a metastatic tumor suppressor gene." (PMID 37461792, 2023).
prostate carcinoma (continued). "CD44 is a well-known marker for “stem-like” cells in prostate cancer." (PMID 37476073, 2023). "Furthermore, SNAI1 plays a critical role in the aggressiveness of prostate cancer by increasing the expression of CD44 and vimentin." (PMID 37476073, 2023). "PFKFB4 mediates CD44-driven proliferation in prostate cancer cells." (PMID 37919747, 2023). "A CD44 drug delivery system based on thiolated chitosan, surface functionalized with hyaluronic acid proved to be an ideal approach for delivery of oncolytic measles virus to prostate cancer tumors." (PMID 37283735, 2023). "Therefore, we measured CD133 and CD44/133 in all prostate cancer subtypes; the results showed a similar trend." (PMID 37476073, 2023). "Indeed, miR34a decisively represses CD44 to inhibit prostate cancer stem cells and metastasis, indicating the direct involvement and pivotal role of both CD44 and miR34a in cancer progression versus cancer prevention." (PMID 37149609, 2023). "Furthermore, we identified a higher percentage of CD44-overexpressed subclonal population (scRNA-seq) in aggressive taxane-resistant DUTXR compared with taxane-sensitive DU145 prostate cancer subtypes." (PMID 37476073, 2023). "Curcumin induces cytotoxicity against CD44- cells and CD44+ prostate cancer cells." (PMID 37663388, 2023). "Furthermore, CD147 stimulates the production of hyaluronic acid (HA), which promotes tumor chemotolerance by interacting with CD44 and HA receptors in prostate cancer." (PMID 36012604, 2022). "In addition, similar to our results, previous studies on prostate cancer showed that CDC20 maintained the self-renewal ability of CD44+ prostate CSCs by promoting nuclear translocation and transactivation of β-catenin." (PMID 35800227, 2022). "CUR inhibited the proliferation, invasion, and tumorigenicity of prostate cancer stem cells HuPCaSCs (CD44+/CD133+ subpopulation isolated from prostate cancer cell lines Du145 and 22RV1) by increasing the expression of miR-145, which prevents cell proliferation by decreasing Oct4 expression." (PMID 35744941, 2022). "Interestingly, CD44+/α2β1hi/CD133+ prostate cancer cells have self-renewal ability and can differentiate into prostate cells that can express AR and PAP." (PMID 35342431, 2022). "Furthermore, CD147 is closely related to CD44, which enhances the metastatic ability and chemoresistance of prostate cancer." (PMID 36012604, 2022). "Downregulation of CD44 or FUT1 genes significantly reduced F77-induced apoptosis in prostate cancer cell lines, suggesting that the binding site of F77 may require fucosylation modification." (PMID 35936713, 2022). "In total, 60% of primary prostate cancer tissues were moderately or strongly positive for CD44." (PMID 35457063, 2022). "At present, some prostate cancer stem cell markers such as CD44 and CD133 have been widely studied." (PMID 35342431, 2022). "In contrast, another study of CD44 isoform expression in prostate cancer concluded that CD44s promoted tumour initiation, cell proliferation, invasion and migration, providing evidence of the correlation between total CD44 expression and prostate cancer progression for CD44s only." (PMID 34944493, 2021). "A previous study reported that the CD44 expression was downregulated by miR-34a in prostate cancer." (PMID 34681583, 2021). "Sam68 is localized in the structure of SGs within the nucleus as a result of DNA damage.Sam68 is up-regulated in prostate cancer and enhances resistance to genotoxic stress.Mitoxantrone-induced nuclear stress also impacts CD44 splicing by following the location of sam68 in the structure of SGs." (PMID 35004322, 2021). "In the PC3 prostate cancer cell line, CD44 was discovered to carry the mAb F77 (a developed prostate cancer-specific mAb) epitope at the exon 14 region, in which F77 induced apoptosis in this cell line in a CD44-dependent manner." (PMID 34944493, 2021).
prostate carcinoma (continued). "As CD44 has a role in molecular interactions, signaling and functions in the nervous system, novel functional roles in relation to its role in prostate cancer progression and neuron-like phenotype may be discovered." (PMID 33572108, 2021). "Through the activation of the Hippo-YAP oncogene signalling pathway, CD44 promoted invasion and migration of docetaxel-resistant prostate cancer cells, which had a larger CD44+ population and positively correlated with poor survival of prostate cancer patients." (PMID 34944493, 2021). "CD44+ cell population increased after radiation in prostate cancer patients." (PMID 33712005, 2021). "CD44 has been reported as a cell surface marker for some breast and prostate cancer stem cells." (PMID 32155897, 2020). "CD44 has been shown to be involved in drug resistance of cancers including prostate cancer." (PMID 32642575, 2020). "Since CD44 is expressed in various tissues, it is likely that we captured exosomes released not only from prostate cancer cells but also from other normal cells, which may in part be responsible for the large variation of exosomal CD44 mRNA copy numbers." (PMID 32642575, 2020). "In this study, we examined CD44 protein and mRNA expression in cell lysates and exosomes isolated from prostate cancer cells, evaluated the effect of CD44v8-10 knockdown on docetaxel sensitivity and measured CD44 mRNA copy numbers contained in serum exosomes in prostate cancer patients." (PMID 32642575, 2020). "In addition, CD44 has been previously reported to be regulated by miR-34a, miR-373 and miR-520c in prostate cancer." (PMID 33473254, 2020). "An experiment conducted on CD44+ prostate cancer stem cells provided relevant information that apigenin co-administrated with cisplatin stimulated the therapeutic effects of cisplatin by inducing a series of modulatory effects on the expression of essential proteins and enzymes." (PMID 31936346, 2020). "CD44 has been investigated as a potential therapeutic target for prostate cancer." (PMID 32183880, 2020). "Importantly, we demonstrate for the first time, that miR-4287 is a key negative regulator of prostate cancer stemness marker CD44 and EMT mediator SLUG." (PMID 33473254, 2020). "Recent study reported that SPP1 can increase CD44 expression in prostate cancer cells." (PMID 33324676, 2020). "AR had been demonstrated to reduce cancer stemness by repression of CD44 and SOX2, on the contrary, loss of AR expression could upregulate STAT3 expression and lead to promote development of cancer stemness in prostate cancer cells." (PMID 32365531, 2020). "Furthermore, 167 prostate cancer biopsy specimens were analyzed in terms of correlations of IL-6 and CD44 levels with clinical patient characteristics." (PMID 31315262, 2019). "Thus, the Hypoxia-inducible factor 1 alpha (HIF-1 alpha) was found to be highly expressed in purified putative murine (Sca-1+/CD49f+) and human (CD44+/CD49f+) prostate cancer stem cell populations." (PMID 31366128, 2019). "COL7A1 is highly expressed in CD133+/CD44+ prostate cancer spheroids." (PMID 31334229, 2019). "Therefore, activating IL-6/STAT3 signaling plays an important role in the induction of CD44-positive prostate cancer." (PMID 31315262, 2019). "Furthermore, IHC data on ectopic tumors (Figure A2a) confirmed that LTB prostate cancer exhibited higher levels of CD44." (PMID 31315262, 2019). "Androgen receptor modulates the expression of CD44 in prostate cancer cells." (PMID 31331331, 2019). "Thus, the study of PDXs contributed to better understand the role of REST, a transcription factor inducing EMT in prostate cancer cells and stemness acquisition via direct transcriptional repression of Twist1 and CD44." (PMID 31366128, 2019).
prostate carcinoma (continued). "As part of the Reproducibility Project: Cancer Biology, we published a Registered Report, that described how we intended to replicate selected experiments from the paper ‘The microRNA miR-34a inhibits prostate cancer stem cells and metastasis by directly repressing CD44’." (PMID 30860027, 2019). "It potently hinders prostate cancer metastasis through repressing CD44." (PMID 29515800, 2018). "We detected F77-glycosylated CD44 in the sera of men diagnosed with primary prostate cancer." (PMID 29423071, 2018). "CSCs in many solid tumors, including cancers of the prostate, breast, pancreas, head and neck, and ovary have been identified using the cell surface adhesion molecule CD44, either individually or in combination with other cell surface markers such as CD133, integrin and ALDH1A19,12." (PMID 29386546, 2018). "Interestingly, the fraction of the CSC-like CD44+/CD24-subpopulation differs among various prostate cancer cell lines and comprises only 0.04% of LNCaP cells compared to ∼11% of PC-3 cells." (PMID 30542512, 2018). "In addition, to analyze CD44 expression also in cells selected after chemotherapeutic agent, we used docetaxel, which is considered standard first-line therapy in prostate cancer cases following resistance to androgen deprivation therapy." (PMID 30112117, 2018). "Our study also suggests that serum levels of F77-glycosylated CD44 may have potential utility to facilitate the diagnosis or prognosis of prostate cancer." (PMID 29423071, 2018). "The roles of CD44 isoforms have also been investigated in prostate cancer." (PMID 29747682, 2018). "Since CD44 is a target of F77-related glycosylation, we next investigated whether this glycosylated form of CD44 could be detected as a secreted protein in the culture media of prostate cancer cells, or in sera from men with prostate cancer." (PMID 29423071, 2018). "But whether CD44 acts as suppressor gene in human prostate cancer in different stage is still under debate." (PMID 29747682, 2018). "Thus, CD44 can modulate the aggressive phenotype of prostate cancer cells by increasing PFKFB4 expression." (PMID 30234009, 2018). "Since our data suggest that CD44v10 may be most relevant to F77 specific glycosylation in prostate cancer, future studies using an antibody specific to this form of CD44 may yield more relevant data than our current ELISA." (PMID 29423071, 2018). "Next, studies also identified CD44+/CD24− prostate cancer cells in established prostate cancer cell lines and showed that these subpopulations were more invasive, tumorigenic and were able to differentiate into mature tumor cells expressing highly aggressive phenotype." (PMID 28758908, 2017). "Indeed, we found that the clones that highly expressed E-cadherin (Du145-EL and PC3/M-EL) contained many more CD44+/CD24- prostate cancer TICs than the E-cadherin-low clones (Du145-ML and PC3/M-ML)." (PMID 29137367, 2017). "The apoptotic effect of TRAIL in combination with taxanes have been tested in the whole population of PC3 and DU145 prostate cancer cells, but also in CD44+/CD24− prostate cancer stem cells subpopulation within both cell lines to examine if this compounds can augment the anti-cancer effect of TRAIL." (PMID 28758908, 2017). "MicroRNA-34a inhibits prostate cancer metastases by directly repressing CD44." (PMID 28388883, 2017). "CD44+/CD24− cells are a putative cancer stem cells subpopulation in prostate cancer." (PMID 28758908, 2017). "Taken together, CD44 could modulate aggressive phenotype of prostate cancer cells, by regulation of the expression of PDK1 and PFKFB4." (PMID 29029419, 2017). "In particular, miR-708-5p expression was suppressed in CD44+ prostate cancer cell populations." (PMID 29050362, 2017). "Furthermore, in prostate cancer cores from 73 patients, CD44 expressing cells were also positive for chromogranin A, a neuroendocrine cell marker." (PMID 28690641, 2017).
prostate carcinoma (continued). "Another study showed that early intervention with a Syndecan-1 inhibitor (OGT2115) or RNAi-mediated Syndecan-1 silencing in a transgenic mouse model of prostate cancer reduced the incidence of adenocarcinoma and the number of c-kit(+)/CD44(+) cells in cancer foci." (PMID 28270211, 2017). "Additionally, ALDHhi CD44+α2β1+ cells increased with castration resistance in mice implanted with prostate cancer cell line xenografts and, when isolated from patients, displayed potential self-renewal capacity based on colony and spheroid formation." (PMID 28690641, 2017). "miR-34 has been shown to be repressed in CD44+ prostate cancer cells." (PMID 28783103, 2017). "Activation of TGF-β signal expanded the CD44+CD24- population in prostate cancer cells through downregulating poly r(C) binding protein (PCBP)-1, which suggested that TGF-β might regulate PCSC maintenance." (PMID 28400729, 2017). "In addition, miR-708 was consistently downregulated in prostate cancer cell lines, which resulted in prostate cancer development and progression through regulation of CD44 and Akt2 expression." (PMID 27092874, 2016). "miR-34a negatively regulates CD44 and inhibits prostate cancer regeneration and metastasis." (PMID 26902416, 2016). "MiR-34a can repress prostate cancer stem cells and metastasis through targeting CD44." (PMID 27580177, 2016). "Prostate cancer stem cells have been described to express surface marker CD44." (PMID 27034170, 2016). "Enforced expression of miR-34a inhibited prostate cancer stem cells and metastasis by directly repressing CD44, indicating that miR-34a is a key negative regulator of prostate CSCs and could be a novel therapeutic agent against prostate cancers." (PMID 26580663, 2015). "What's more, ADT (androgen deprivation therapy) in prostate cancer could promote the EMT with increased CD44+ stem-like cells." (PMID 25797261, 2015). "Indeed, PC3 and DU-145 prostate cancer cells overexpressing SULF2 exhibited increased levels of CD44, vimentin, and N-cadherin." (PMID 25887999, 2015). "Recent papers identified CD44+CD24− cells in different prostate cancer cell lines." (PMID 26593898, 2015). "In their 2011 Nature Medicine paper, Liu and colleagues elucidated the importance of a particular microRNA, miR-34a, on the action of CD44+ prostate cancer putative CSCs, demonstrating that miR-34a was barely expressed in CD44+ CSCs and had tumor suppressing properties." (PMID 26231042, 2015). "In prostate cancer, CD44 is inhibited by rapamycin via its inhibition of mTOR signaling." (PMID 26202311, 2015). "Furthermore, miR-34a was under-expressed in CD44+ prostate cancer cells, and CD44 was identified and validated as a direct and functional target of miR-34a." (PMID 26062441, 2015). "Thus, prostate cancer cells were immunostained for CD44, vimentin, and N-cadherin and the presence as well as their quantity analyzed by flow cytometry." (PMID 25887999, 2015). "CD44 and α2β1 integrin are markers that to enrich for a prostate cancer stem cell population." (PMID 24587067, 2014). "Therefore, cluster of differentiation 133 (CD133)+high/CD44+high prostate CSCs were isolated from the DU145 human prostate cancer cell line." (PMID 25216351, 2014). "For example, prostate cancer (PCa) metastasis and chemoresistance may be modulated by the increased expression of either CD44 or CD147 as a result of activation of the PI3K and MAPK pathways." (PMID 25268615, 2014). "Additionally, CD44 and CD147 have been associated with the metastasis and progression of breast or prostate cancer." (PMID 25268615, 2014). "In prostate carcinoma cells, CD44 was even considered as a metastasis-suppressor gene." (PMID 23565227, 2013). "Furthermore, CD44 as a cell surface marker has been identified in some breast and prostate cancer stem cells." (PMID 24101930, 2013). "The role of CD44 isoforms in prostate cancer development and progression needs further elucidation." (PMID 23476138, 2013).